RNF168 (ring finger protein 168)
Diseases named in the same sentence as RNF168 in open-access papers (continued):
Sharing a sentence is not in itself a finding about the gene and the disease.
breast tumour (1 paper, 2016). "To further elucidate the effect of RNF168 expression on the response of breast tumour cells to etoposide, we examined the effect of RNF168 knockdown on etoposide-induced cytotoxicity of T47D and MDA-MB-231 cell lines." (PMID 27558965, 2016).
colorectal adenocarcinoma (1 paper, 2024). The most common type of colorectal carcinoma. "For example, in colorectal adenocarcinoma, SENP1 reduces the SUMOylation of RNF168 when DNA damage occurs, facilitating its LLPS, enhancing non-homologous end joining (NHEJ) repair efficiency, and consequently strengthening cancer cell resistance to DNA-damaging agents." (PMID 38546385, 2024).
colorectal cancer (1 paper, 2023). A primary or metastatic malignant neoplasm that affects the colon or rectum. "In colorectal cancer, SENP1 inhibits RNF168 phase separation, which in turn promotes DNA damage repair and drug resistance in colorectal cancer." (PMID 37980165, 2023).
COVID-19 (1 paper, 2021). A disease caused by infection with severe acute respiratory syndrome coronavirus 2. "We conducted whole-exome sequencing in 233 hospitalized COVID-19 patients and identified four PID gene (UNC13D, AP3B1, RNF168, DHX58) variants were significantly enriched in COVID-19 patients experiencing severe cytokine storms." (PMID 33867526, 2021).
endothelial dysfunction (1 paper, 2025). In vascular diseases, endothelial dysfunction is a systemic pathological state of the endothelium (the inner lining of blood vessels) and can be broadly defined as an imbalance between vasodilating and vasoconstricting substances produced by (or acting on) the endothelium. "With this approach, we revealed translational regulation of SND1 as a key mediator of sunitinib-induced endothelial dysfunction, which suggests that targeting SND1 translation and the SND1 downstream factors UBE2N, RNF8, and RNF168 is a potential therapeutic strategy for vascular dysfunction." (PMID 39895626, 2025). "Furthermore, wound-healing assays revealed that the protective effects of UBE2N OE on sunitinib-induced endothelial dysfunction were reversed by inhibition of RNF8 or RNF168 but not HLTF and SHPRH." (PMID 39895626, 2025).
gastric cancer (1 paper, 2023). A primary or metastatic malignant neoplasm involving the stomach. "Thus, RNF168 might be used to develop effective therapies for gastric cancer treatment." (PMID 36771081, 2023). "Previous studies have shown that RNF168 is lowly expressed in human gastric cancer tissues and can directly interact with RHOC and promote the degradation of RHOC by increasing the ubiquitination level of RHOC, thus affecting the function of gastric cancer cells." (PMID 36771081, 2023).
glioma (1 paper, 2019). A benign or malignant brain and spinal cord tumor that arises from glial cells (astrocytes, oligodendrocytes, ependymal cells). "Our results demonstrate that G0S2 regulates glioma radioresistance through mTOR/S6K/ RNF168/53BP1-regulated DNA repair." (PMID 30953555, 2019). "Modulation of G0S2 expression affects GBM responses to IR treatments in vitro and in vivo through mTOR/S6K/RNF168/53BP1-regulated DNA repair, suggesting G0S2 as a potential mediator of glioma responses to IR." (PMID 30953555, 2019).
head and neck cancer (1 paper, 2024). A primary or metastatic malignant neoplasm affecting the head and neck. "Both HPV+ cervical and head and neck cancer cells express high levels of RNF168 mRNA, which is likely an adaptation to chronic E7-mediated RNF168 sequestration." (PMID 38730612, 2024).
Hereditary breast cancer (1 paper, 2017). Breast carcinoma that has developed in relatives of patients with history of breast carcinoma. "In total, four of the recurrent mutations showed significant (TEX15 c.7253dupT and FANCD2 c.2715 + 1G > A) or borderline association (TEX15 c.8325G > A and RNF168 c.640_644del5) with hereditary breast cancer in the Northern Finnish cohort." (PMID 28386063, 2017).
herpesvirus infection (1 paper, 2011). "This study highlights important parallels between recognition of cellular DNA damage and recognition of viral genomes, and adds RNF8 and RNF168 to the list of factors contributing to the intrinsic antiviral defense against herpesvirus infection." (PMID 21698222, 2011).
immunoglobulin deficiency (1 paper, 2017). "A comparison with the two previously identified patients indicates immunoglobulin deficiency, cellular radiosensitivity, and increased AFP levels as hallmarks of RNF168 deficiency." (PMID 29255463, 2017).
intraepithelial neoplasia (1 paper, 2022). A precancerous neoplastic process that affects the squamous, glandular, or transitional cell epithelium without evidence of invasion. "Interestingly, we also identified lower methylation of cg01550828, associated with gene RNF168 as a biomarker for pathogenesis of intermediate status (precancerous lesions/intraepithelial neoplasia), providing a novel approach for predicting the precancerous lesion stage." (PMID 36249027, 2022).
lung carcinoma (1 paper, 2023). "Based on our siRNA screening results, RNF168 inhibition resulted in significant inhibition of cell viability across all three tested KRAS-mutant lung cancer cell lines." (PMID 36858798, 2023).
primary immunodeficiencies (1 paper, 2017). "RNF168 has occasionally been included on sequencing panels for primary immunodeficiencies, and in one study two unspecified RNF168 missense variants were reported in 1/33 patients." (PMID 29255463, 2017).
prostate tumors (1 paper, 2024). "We propose that future studies should explore this RAD18/UBC13/PALB2/RNF168 fork recovery pathway in additional models of BRCA1-deficient cancers, including breast and prostate tumors." (PMID 38943334, 2024).
cancer (31 papers, 2010 to 2025). A tumor composed of atypical neoplastic, often pleomorphic cells that invade other tissues. "Our work reveals a previously unappreciated role of the RAD18, UBC13, PALB2 and RNF168 pathway in replication fork recovery in BRCA1-deficient cancer cells." (PMID 38943334, 2024). "Downregulation of RNF168 protein expression sensitizes cancer cells, particularly BRCA1-deficient cells, which are resistant to DNA damage agents." (PMID 39487119, 2024). "Considering DNA damage results in pausing the cell cycle, and can even eventually induce apoptosis if unrepairable, targeting RNF168 is one possible method to increase the genomic instability burden of cancer cells and eventually cause death." (PMID 37760968, 2023). "Such RNF168 deficiency-induced R-loop accumulation can heighten the sensitivity of cancer cells to G4/R-loop-stabilizing drugs such as PARP inhibitors (PARPi), pyridostatin, and irradiation." (PMID 36750826, 2023). "Recent studies have found that RNF168 is significantly implicated in the occurrence and development of various cancers." (PMID 36771081, 2023). "Ubiquitination of H2A.X is less studied in cancer but the E3 ligases RNF168 and RNF8 have been implicated in cancer and genomic instability." (PMID 29495465, 2018). "Therefore, BRCA1-deficient cancer cells need to reduce the protein level of RNF168 to maintain a certain HR level in order to ensure survival." (PMID 36771081, 2023). "Cancers with these mutations may reduce RNF168 activity as a means of promoting DNA end resection and inducing RAP80-mediated RINGless BRCA1-P loading, and consequently PARPi resistance." (PMID 34408138, 2021). "Considering the unambiguous association between RNF168 and PALB2, inhibiting RNF168 signaling in BRCA1-insufficient cancers may be an effective therapeutic strategy." (PMID 32185139, 2020). "Further studies are also required to determine whether loss of RNF168 expression or its inactivation correlate with resistance to anti-cancer chemotherapeutics that target TOP2 in cancer patients." (PMID 27558965, 2016). "Furthermore, missense mutations, such as R407T, P4L, and S59L, may impact the functionality of RNF168, linking these PTMs and mutations to cancer progression." (PMID 39996778, 2025). "Indeed, our data show that RAD18 recruitment to chromatin upon HU treatment depends on RFN168 in BRCA1-deficient cancer cells, indicating that RNF168 might act upstream of RAD18 to facilitate its recruitment to degraded forks and fork recovery." (PMID 38943334, 2024). "Thus, the BRCA1 RING domain could determine phenotypes associated with modulation of RNF168 activity in cancer." (PMID 34408138, 2021). "However, overexpression of RNF168 may trigger abnormal repair mechanisms, imbalancing this process and causing cancer." (PMID 33493132, 2021). "RNF168 influences the sensitivity of cancer cells to specific chemotherapeutic agents by promoting distinct forms of ubiquitination, resulting in the degradation of proteins and impacting how cells respond to treatment." (PMID 39996778, 2025). "Specifically, RNF168 can participate in cancer progression by regulating the stability of key proteins in the cell signaling pathway and affect the proliferation and invasion of cancer cells." (PMID 36771081, 2023). "Another example of cancer-relevant chromatin remodeling mechanisms is co-operation between RNF168 and TP53BP1, both related to epigenetic gene regulation and DNA damage response." (PMID 36858798, 2023). "The activated mTORC1-S6K pathway destabilizes RNF168 in a Ser60 phosphorylation-dependent manner, thus promoting genomic instability and participating in the pathogenesis of cancer." (PMID 36771081, 2023). "RNF168 can participate in the occurrence of cancer through a variety of ways and is closely related to the drug resistance of cancer cells." (PMID 36771081, 2023).
cancer (continued). "RNF168 plays a key role in DNA damage repair, through which it can affect the occurrence and development of cancer." (PMID 36771081, 2023). "The present review exposed the structure and function of E3 ubiquitin ligase RNF168 and its relationship with cancer, especially the role of RNF168 in carcinogenesis and development." (PMID 36771081, 2023). "Previous studies have shown that RNF168 plays an important role in the drug resistance of cancer cells and the progression of multiple cancers, on we will elaborate in the following chapters." (PMID 36771081, 2023). "UBE2N, along with RNF168, is involved in DNA damage response-related ubiquitin signaling, and this pathway is frequently altered in cancers." (PMID 33963218, 2021). "RNF168 expression and signaling is deregulated in tumors and cancer cell lines by mechanisms that include increased mRNA expression, downregulation of TRIP12 and UBR5 proteases, as well as reduced expression of enzymes that de-ubiquitinate ub-H2AX." (PMID 32182354, 2020). "Subsets of BRCA1 mutant cancers reported in the TCGA database show increased RNF168 mRNA expression." (PMID 32182354, 2020). "Here, we report that RNF168 interacts with TOP2α to mediate its polyubiquitylation, and we further show that RNF168 deficiency confers resistance to ICRF-193, a TOP2 catalytic inhibitor, and etoposide (VP-16), a TOP2 poison and cytotoxic anti-cancer drug." (PMID 27558965, 2016). "Our data also demonstrate novel roles of Rnf168 in spermatogenesis, maintenance of genomic integrity and cancer, and therefore, further highlight the other important physiological functions of this molecule." (PMID 21552324, 2011). "Indeed, various cancers including breast, ovarian and prostate cancers express high levels of RNF168 that correlate with a poor prognosis and reduced survival rate." (PMID 38985307, 2024). "Therefore, perhaps unsurprisingly, tight regulation of RNF168 is required to prevent the onset of neurodegenerative disease, immunodeficiency or cancer development." (PMID 38985307, 2024). "However, the research on the clinical significance of RNF168 and its role in cancer proliferation or inhibition is still elusive." (PMID 36771081, 2023). "In contrast, RNF168 is also lowly expressed in some cancers." (PMID 36771081, 2023). "Whether RNF168 acts as an oncogene or a tumor suppressor is closely related to the target of RNF168 in different cancers." (PMID 36771081, 2023). "The protein level of RNF168 is also regulated by post-translational modification, so the upstream protein that regulates the expression of RNF168 can also be used as a potential target for cancer treatment." (PMID 36771081, 2023). "Here, we hope to clarify the great potential for targeting RNF168 as a cancer treatment target." (PMID 36771081, 2023). "Moreover, deletion of RNF168 inhibits the chromatin ubiquitin pathway and enhances the sensitivity of cancer cells to the bioavailable derivative of quarfloxin CX-5461." (PMID 36771081, 2023). "Therefore, the RNF168/H2A signaling axis represents another mechanism for pathological activation of Pol η and elevated mutagenesis in cancer cells." (PMID 34663880, 2021). "RNF168 is aberrantly overexpressed in many cancers, frequently due to gene amplification." (PMID 34663880, 2021). "Based on these findings, we could conclude RNF168 play an unconventional role in regulating ERɑ signalling and ERɑ‐positive cancer phenotype." (PMID 29974997, 2018). "Importantly, our data further highlight novel roles of Rnf168 in spermatogenesis, genomic integrity and cancer." (PMID 21552324, 2011).
cancer (continued). "Additionally, the abnormal expression of RNF168 has been identified in many cancers." (PMID 36771081, 2023). "The usage of a targeted therapy drug is context-dependent, and RNF168 inhibition may not be beneficial in all cancers with BRCA1 mutations." (PMID 37760968, 2023). "In addition, our data suggest that these functional interactions between RNF168 and TOP2α may play important roles in the response and resistance of tumors to anti-cancer drugs that target TOP2." (PMID 27558965, 2016). "RNF168, RNF126, and CUL1 are involved in several cellular functions which are critical for the hallmarks of cancer." (PMID 37760968, 2023). "This section discusses ubiquitin pathway-targeting drugs and some of the strategies for the development as well as the potential utilization of RNF126, RNF168 and the CUL1 and SCF complex and its related factors for cancer therapy and diagnostics." (PMID 37760968, 2023). "RNF126, RNF168 and CUL1 are involved in DNA damage response (DDR), DNA double-strand break (DSB) repair, cell cycle regulation, and ultimately, cancer cell proliferation control." (PMID 37760968, 2023). "For example, upregulation of the H2AK15 E3 ubiquitin ligase RNF168 is critical for the resistance of cancer cells to endogenous or treatment-induced proteotoxic stress and, therefore, RNF168 may be a promising target for a therapeutic strategy exploiting aberrant histone ubiquitination in cancers." (PMID 30781493, 2019). "Here the authors identify TOP2a as substrate for RNF168 and USP10; providing a link between the RNF168/USP10 axis, TOP2a and the response to anti-cancer drugs that target TOP2." (PMID 27558965, 2016). "SKBR3, T47D and MDA-MB-231 cancer cell lines, which highly express RNF168, were more sensitive to etoposide compared with the low RNF168-expressing MCF7 and MDA-MB-415 cancer cell lines." (PMID 27558965, 2016). "The third approach includes inhibiting enzymatic function, blocking PPI or other mechanisms, which might be the desired mechanism for cancer therapy when considering the role of RNF126, RNF168, and CUL1." (PMID 37760968, 2023). "Similarly, RNF168 was shown to be lowly expressed in lung adenocarcinoma tissues and promote the degradation of RHOC protein by ubiquitinating RHOC, thus suppressing the cancer stem cell (CSC)-like traits of non-small cell lung cancer (NSCLC) cells." (PMID 36771081, 2023). "Overexpression of WT RNF168 resulted in transcriptional activation, and consistent with the model that RNF168 S481 is constitutively phosphorylated in cancer cells, this effect was indistinguishable from the effects with the constitutive phosphorylation mimicking S481D mutant." (PMID 36858798, 2023). "The TCGA papers provide essential data demonstrating the increased expression of RNF168 in HPV+ cancers, which provides important insight into how HPV proteins may subvert DSB signaling and repair pathways, potentially highlighting novel therapeutic avenues in these cancers." (PMID 38747609, 2024). "Thus, in the absence of BRCA1, excessive RNF168 expression may drive BIR, and contribute to the mutational signatures observed in BRCA1-mutated cancers." (PMID 32182354, 2020).